SMARCB1 (SWI/SNF related BAF chromatin remodeling complex subunit B1)
Diseases named in the same sentence as SMARCB1 in open-access papers (continued):
Sharing a sentence is not in itself a finding about the gene and the disease.
schwannoma (continued). "Nevertheless, it is plausible that the events which drive schwannoma growth differ depending upon the presence or absence of a germline PV in one of the three schwannoma predisposition genes (NF2, SMARCB1 and LZTR1)." (PMID 40794298, 2025). "These SMARCB1 PV carriers were unaffected in the sense that they did not develop MRT or symptomatic schwannomas." (PMID 40794298, 2025). "Molecular characterization using focused next-generation sequencing did not identify SMARCB1 or NF2 mutations, alterations previously associated to schwannoma at other anatomical sites." (PMID 37535242, 2023). "The affected family members did not appear to harbour germline mutations in SMARCB1, LZTR1, or NF2; nor were somatic mutations of these genes detected in two schwannomas from two family members." (PMID 27921248, 2017). "Schwannoma tumorlets in the DRGs of mGFAP-Cre;Smarcb1flox/flox;Nf2flox/flox mice were negative for SMARCB1 and merlin staining, about 60% were positive for S100 protein staining, and all were positive for GFAP and FABP7." (PMID 28824165, 2017). "Furthermore, immunohistochemical staining indicated normal protein expression levels of SMARCB1, LZTR1, and NF2 in both schwannomas." (PMID 27921248, 2017). "This instability results in immunologically nonreactive SMARCB1 protein degradation products in a proportion of the schwannoma cells." (PMID 27921248, 2017). "Importantly, the human-zebrafish copy number loss intersections included all 3 genes whose hereditary mutation is known to predispose individuals to Schwann cell tumors (neurofibromas, schwannomas and MPNSTs) - NF1, NF2 and SMARCB1." (PMID 24009526, 2013). "However, significant differences in the molecular profiles of schwannomas derived from patients with either LZTR1- or SMARCB1-related SWN were not obvious." (PMID 40794298, 2025). "However, no detectable mosaicism was found in six patients without SMARCB1 and LZTR1 mutations in their blood, as determined by analysing multiple schwannomas from these patients." (PMID 27921248, 2017). "However, it is unclear whether these apparently unaffected SMARCB1 PV carriers had clinical signs of SMARCB1-related SWN since they were not investigated by MRI, especially later in life, in order to exclude the occurrence of asymptomatic schwannomas." (PMID 40794298, 2025). "The SH3PXD2A-HTRA1 fusion gene was detected in 2/24 (8.3%) of schwannomas from patients with SMARCB1-related SWN, and in 13/64 (20.3%) of schwannomas from patients with LZTR1-related SWN which is not significantly different." (PMID 40794298, 2025). "The expression level of SMARCB1 in both the tumor tissue and cell line was significantly downregulated when compared to non-SWN related schwannomas." (PMID 26657314, 2015).
sinonasal carcinoma (41 papers, 2018 to 2026). "SMARCB1-deficient sinonasal carcinomas predominantly involved the ethmoid sinus (6 of 8 patients), presenting epistaxis (7 of 10 patients), nasal obstruction (5 of 10 patients), and ocular symptoms (4 of 10 patients)." (PMID 42074742, 2026). "SMARCB1-deficient sinonasal carcinoma (SDSC) is a rare, highly aggressive malignancy with limited therapeutic options and no established preclinical models." (PMID 42070010, 2026). "Single nucleotide polymorphism (SNP) array and EWSR1 gene fluorescence in situ hybridization (FISH) analyses were conducted on SMARCB1-deficient sinonasal carcinomas." (PMID 40366517, 2025). "SMARCB1-deficient sinonasal carcinoma is rare, with fewer than 200 cases reported in the literature since its discovery in 2014." (PMID 40366517, 2025). "A comprehensive targeted next-generation sequencing study on a relatively large cohort of the SMARCB1-deficient sinonasal carcinoma (n = 22) revealed the loss of at least one SMARCB1 allele, with most cases (13/19, 68%) showing homozygous deletion." (PMID 40366517, 2025). "SMARCB1-deficient sinonasal carcinomas constitute 4.7% of sinonasal carcinomas in our cohort; and none were SMARCA4-deficient carcinomas." (PMID 40366517, 2025). "A subset of the SMARCB1-deficient sinonasal carcinoma has been reported to be p16 positive in the literature." (PMID 40366517, 2025). "SMARCB1-deficient carcinomas account for 4.7% of sinonasal carcinomas in this single-institution cohort, while SMARCA4-deficient tumors are even rarer, with none identified." (PMID 40366517, 2025). "Extended copy number loss of genes neighboring SMARCB1 has been reported in other SMARCB1-deficient mesenchymal tumors and SMARCB1-deficient sinonasal carcinoma as well." (PMID 40366517, 2025). "SMARCB1-deficient sinonasal carcinomas exhibit a broad spectrum of morphologic and immunohistochemical features." (PMID 40366517, 2025). "One SMARCB1-deficient sinonasal carcinoma failed the DNA quality control testing, while SNP array analysis was successfully performed on the remaining 6 cases." (PMID 40366517, 2025). "The majority of SMARCB1-deficient sinonasal carcinomas demonstrate homozygous deletion of the SMARCB1 gene and frequently harbor gene loss flanking the SMARCB1 gene, including the EWSR1 gene." (PMID 40366517, 2025). "Four SMARCB1-deficient sinonasal carcinomas exhibited basaloid morphology, two displayed eosinophilic tumor morphology, and one had mixed morphology." (PMID 40366517, 2025). "Four SMARCB1-deficient sinonasal carcinomas exhibited a basaloid (“blue tumor”) appearance, morphologically resembling nonkeratinizing squamous cell carcinoma (SCC) of the sinonasal tract." (PMID 40366517, 2025). "The clinicopathologic data from our study reiterate the aggressive behavior of the SMARCB1-deficient sinonasal carcinoma." (PMID 40366517, 2025). "The recognition of SMARCB1-deficient sinonasal carcinoma (SDSNC) as a distinct entity emerged recently, with its initial description in 2014." (PMID 39925590, 2025). "Molecular and genomic studies performed on a subset of SMARCB1-deficient sinonasal carcinomas using FISH or next-generation sequencing have revealed complex molecular alterations underlying SMARCB1 protein loss." (PMID 40366517, 2025). "The majority of SMARCB1-deficient sinonasal carcinomas exhibited basaloid morphology, with many displaying an exophytic component, almost indistinguishable from the sinonasal nonkeratinizing SCC." (PMID 40366517, 2025). "SMARCB1-deficient sinonasal carcinomas account for 4.7% of carcinomas of the sinonasal tract in this single-institution cohort, while no cases of SMARCA4-deficient sinonasal carcinoma were identified." (PMID 40366517, 2025). "SWI/SNF‐related matrix‐associated actin‐dependent regulator of chromatin subfamily B member 1 (SMARCB1) (integrase interactor 1)-deficient sinonasal carcinoma (SDSNC) is a rare and aggressive malignancy of the head and neck." (PMID 39925590, 2025).
sinonasal carcinoma (continued). "Our study re-illustrates the wide morphologic and immunophenotypic spectrum of the SMARCB1-deficient sinonasal carcinoma." (PMID 40366517, 2025). "Expression of CDX2 and hepatocyte-specific antigen has been reported in the SMARCB1-deficient sinonasal carcinoma previously." (PMID 40366517, 2025). "SMARCB1-deficient sinonasal carcinomas exhibit a broad morphologic and immunohistochemical spectrum, underscoring the importance of performing relevant INI1 and BRG1 immunohistochemical staining when classifying sinonasal tumors." (PMID 40366517, 2025). "Immunophenotypically, a subset of SMARCB1-deficient sinonasal carcinomas exhibited features that overlap with the SCC, and some tumors expressed neuroendocrine markers." (PMID 40366517, 2025). "The reported frequency of SMARCB1-deficient sinonasal carcinomas ranges from 2 to 7%, based on a small number of systematic cohort studies." (PMID 40366517, 2025). "SMARCB1-deficient sinonasal carcinoma is often diagnosed as an undifferentiated or poorly differentiated carcinoma, with pathological evidence of rhabdoid and basaloid cells." (PMID 39398818, 2024). "Treatment of SMARCB1-deficient sinonasal carcinoma often involves multimodality therapy such as surgical resection or chemoradiotherapy." (PMID 39398818, 2024). "In our case, there are no evident basaloid or plasmacytoid/rhabdoid tumor cells, which are typical histopathologic features of SMARCB1-deficient sinonasal carcinoma." (PMID 38836164, 2024). "Simultaneously, the importance of early and accurate diagnosis of SMARCB1-deficient sinonasal carcinoma will increase." (PMID 38836164, 2024). "In head and neck cancer, SMARCB1-deficient sinonasal carcinoma was first reported in 2014, followed by a series of reports." (PMID 39398818, 2024). "In our case, there were no evident basaloid or plasmacytoid/rhabdoid tumor cells, which were typical histopathological features of SMARCB1-deficient sinonasal carcinoma." (PMID 38836164, 2024). "SWI/SNF complex-deficient sinonasal carcinomas are now well recognized as high-grade malignancies with distinctive deficiencies in the SMARCB1 and SMARCA4 subunits, distinguishing them from other neoplasms such as SNUC or poorly differentiated carcinomas." (PMID 39590317, 2024). "Not only is SMARCB1-deficient sinonasal carcinoma a rare disease but also most lesions are diagnosed at the locally advanced pT4 stage, are prone to recurrence, and have a very poor prognosis." (PMID 38836164, 2024). "Since the first report of a subtype of sinonasal carcinoma characterized by a deficiency of the SMARCB1 gene in 2014 to date, fewer than 200 cases have been reported." (PMID 38836164, 2024). "Herein, we report an extremely rare case of SMARCB1-deficient sinonasal carcinoma with clear cell morphology." (PMID 38836164, 2024). "In our case, no evident basaloid or plasmacytoid/rhabdoid cell morphology was observed, and the tumor cells had clear cell morphology, making it difficult to suspect a SMARCB1-deficient sinonasal carcinoma." (PMID 38836164, 2024). "Reports published in 2014 concerning the head and neck region show that SMARCB1 deficits can be found in sinonasal carcinoma; SMARCB1-deficient sinonasal carcinoma was newly described in the 2017 WHO classification of tumors in the nose and sinus region." (PMID 39398818, 2024). "Glandular differentiation has been very rarely reported in SMARCB1 (INI-1)-deficient sinonasal carcinomas, although it is possible that this feature has been underrecognized." (PMID 38085333, 2024). "In a study analyzing 39 cases of SMARCB1-deficient sinonasal carcinoma, 22 patients were most frequently selected for surgery and chemoradiation, with a disease-free survival rate of 30% during the 11-115 months of follow-up." (PMID 39398818, 2024). "Among these, independent German and American researchers first described a subtype of sinonasal carcinoma characterized by a deficiency of the SMARCB1 gene in 2014." (PMID 38836164, 2024).
sinonasal carcinoma (continued). "On the other hand, in SMARCB1-deficient sinonasal carcinoma, most lesions are diagnosed at the locally advanced pT4 stage, are prone to recurrence, and have a very poor prognosis." (PMID 38836164, 2024). "Regarding therapy, available data on the significance of the distinction between SMARCB1-deficient sinonasal carcinoma and adenocarcinoma as well as their long-term follow-up is limited." (PMID 38491228, 2024). "Histopathologically, SMARCB1-deficient sinonasal carcinoma is characterized by sheet-like, solid, or alveolar growth of tumor cells with basaloid or plasmacytoid/rhabdoid cell morphology." (PMID 38836164, 2024). "Although the number of cases of SMARCB1-deficient sinonasal carcinoma has been increasing in recent years, reports of SMARCB1-deficient tumors in the head and neck regions, except the nose and sinuses, are extremely rare." (PMID 39398818, 2024). "The most common of these four, the SMARCB1 (INI-1)-deficient sinonasal carcinoma, is an aggressive tumor that was first reported in 2014 independently by two research groups." (PMID 38085333, 2024). "Currently, it is also subjected to clinical trials overseas to treat locally advanced SMARCB1-deficient sinonasal carcinoma." (PMID 38836164, 2024). "The largest single-institution study of SMARCB1-deficient sinonasal carcinoma to date reported the outcomes of 19 consecutive patients with SMARCB1 (INI-1)-deficient sinonasal carcinoma treated at the MD Anderson Cancer Center." (PMID 38491228, 2024). "In our case, there are no evident basaloid or plasmacytoid/rhabdoid tumor cells, which are typical histopathological features of SMARCB1-deficient sinonasal carcinoma." (PMID 38836164, 2024). "Immunohistochemically, the neoplastic cells of SMARCB1-deficient sinonasal carcinoma are uniformly pan-cytokeratin positive, focally positive for p63/p40, and negative for NUT and p16." (PMID 38491228, 2024). "SMARCB1 deficiency in a subset of poorly or undifferentiated sinonasal carcinoma was first recognized in 2014 by 2 independent groups followed by a few additional case series, the largest multi-institutional series comprised 39 patients." (PMID 38491228, 2024). "In the head and neck region, there have been many recent cases of SMARCB1-deficient sinonasal carcinoma, but reports of extrasinonasal sites are extremely rare." (PMID 39398818, 2024). "SMARCB1 (INI1)-deficient sinonasal carcinomas represent a group of poorly differentiated carcinomas characterized by the loss or complete inactivation of the SMARCB1 subunit, resulting in a basal-like, anaplastic, and even rhabdoid morphology." (PMID 39590317, 2024). "SMARCB1-deficient sinonasal carcinoma is a newly recognized subtype of sinonasal carcinoma with unique clinicopathologic features that make accurate diagnosis difficult, especially in small biopsy specimens." (PMID 38836164, 2024). "Because SMARCB1-deficient sinonasal carcinoma is progressive and has a poor prognosis, it is necessary to develop targeted therapeutics against SMARCB1-associated molecular abnormalities." (PMID 38836164, 2024). "The immunostaining results, including INI-1 in our case, were also consistent with SMARCB1-deficient sinonasal carcinoma." (PMID 38836164, 2024). "SMARCB1-deficient sinonasal adenocarcinomas lack the basaloid morphology seen in 60–70% of SMARCB1-deficient sinonasal carcinomas and instead display either clear-cut gland formation, cribriform patterns, or mucin production." (PMID 38491228, 2024). "The aggressive SWI/SNF complex-deficient sinonasal carcinomas lack the expression of SMARCA4 or SMARCB1 proteins while displaying relatively monomorphic rhabdoid, plasmacytoid, or epithelioid morphology and infiltrative growth into the surrounding tissue." (PMID 37415052, 2023). "SMARCA4 deficient carcinoma is thought to have a neuroendocrine origin, while SMARCB1 deficient carcinoma represents an emerging poorly differentiated/undifferentiated sinonasal carcinoma." (PMID 37568614, 2023).
sinonasal carcinoma (continued). "There are several recently discovered distinct entities, such as SMARCA4 deficient sinonasal carcinomas and SMARCB1 (INI-1) deficient sinonasal carcinoma." (PMID 37568614, 2023). "This rare variant in the spectrum of SMARCB1-deficient sinonasal carcinoma is defined by presence of unequivocal gland formation." (PMID 35307773, 2022). "SMARCB1 (INI-1)-deficient sinonasal carcinoma is a rare but locally aggressive malignancy of the nasal cavity and paranasal sinuses, representing only about 1% of all head and neck malignancies." (PMID 35805058, 2022). "SMARCB1-deficient sinonasal carcinoma was first described and reported in 2014, and was first recognized as a subset of sinonasal undifferentiated carcinoma in the 4th edition of the World Health Organization’s Classification of Head and Neck Tumors in 2017." (PMID 35805058, 2022). "Diagnosis of SMARCB1-deficient sinonasal carcinoma should be considered in all undifferentiated sinonasal carcinomas." (PMID 35399302, 2022). "Resection was performed, and immunohistochemical studies revealed a complete loss of INI-1, refining the diagnosis to SMARCB1-deficient sinonasal carcinoma." (PMID 35399302, 2022). "SMARCA4-deficient sinonasal carcinoma behaves more aggressively compared to the SMARCB1-deficient tumors; two thirds of patients with follow-up died of their disease within one year." (PMID 35307773, 2022). "SMARCB1-deficient sinonasal carcinoma is a newly described entity, with less than 100 reported cases." (PMID 35399302, 2022). "SMARCB-1 deficient sinonasal carcinoma, first reported in 2014, remains one of the rarest and most poorly understood sinonasal malignancies." (PMID 35805058, 2022). "By immunohistochemistry, SMARCB1-deficient sinonasal carcinomas express uniformly pankeratins (97%) and variably CK5 (64%), p63 (55%) and CK7 (48%)." (PMID 35307773, 2022). "Our institution treated eight patients with SMARCB1-deficient sinonasal carcinoma between January 2014 and December 2021, with the database locked on 31st March 2022." (PMID 35805058, 2022). "SWItch/Sucrose Non-Fermentable (SWI/SNF) -related matrix-associated actin-dependent regulator of chromatin (SMARC) subfamily B member 1 (SMARCB1) deficient sinonasal carcinoma (SdSNC) is a rare variant of sinonasal undifferentiated carcinoma (SNUC)." (PMID 33959255, 2021). "SMARCB1 (INI-1)-deficient sinonasal carcinoma has been identified in about 100 cases so far in the world, showing a poor prognosis, with a mean survival of 22 months." (PMID 34638515, 2021). "With the recent characterization of the SMARCB1-deficient sinonasal carcinoma, a variant showing frankly glandular growth and occasional yolk sac-like pattern has been proposed as a distinctive variant in the spectrum of SWI/SNF-deficient sinonasal carcinomas." (PMID 33428064, 2021). "A maxillectomy was performed for resection and pathology returned a diagnosis of a SMARCB1-Deficient Sinonasal Carcinoma." (PMID 31438887, 2019). "SMARCB1-deficient sinonasal carcinoma (SDSC) is an aggressive subtype of head and neck cancers that has a poor prognosis despite multimodal therapy." (PMID 31438887, 2019). "SWI/SNF complex-deficient sinonasal carcinoma, defined by the loss of SMARCB1 or SMARCA4, was recently recognized as a distinct entity in the 5th edition of the World Health Organization (WHO) Classification of Head and Neck Tumors, highlighting its unique clinicopathologic and molecular profile." (PMID 40366517, 2025). "A distinctive pattern of p16 expression was observed in 5/7 SMARCB1-deficient sinonasal carcinomas." (PMID 40366517, 2025). "All seven SMARCB1-deficient sinonasal carcinoma patients were male." (PMID 40366517, 2025). "SMARCB1-deficient sinonasal carcinoma is a rare tumor, with fewer than 200 cases reported." (PMID 40366517, 2025). "EWSR1 gene FISH analysis was successfully conducted on all SMARCB1-deficient sinonasal carcinomas." (PMID 40366517, 2025).